NLRP3 (NLR family pyrin domain containing 3)
Diseases named in the same sentence as NLRP3 in open-access papers (continued):
Sharing a sentence is not in itself a finding about the gene and the disease.
Cerebral ischemia (172 papers, 2014 to 2026). Restriction of arterial blood supply to the brain associated with insufficient oxygenation to support the metabolic requirements of the tissue. "Previous studies have implicated the NLRP3 inflammasome, a key mediator of neuroinflammation, in cerebral ischemia/reperfusion (I/R) injury." (PMID 41254936, 2025). "The inflammatory effect caused by the activation of the NLRP3 inflammasome plays an important role in cerebral ischemia-reperfusion injury." (PMID 39199474, 2024). "Recent studies have implicated that inhibition of the NLRP3 inflammasome by enhancing autophagy prevented neuronal deficits during cerebral ischemia-reperfusion." (PMID 36467606, 2022). "Minocycline inhibited NLRP3 inflammatory bodies’ activation and associated inflammatory responses in mouse models, significantly improving brain injury induced by cerebral ischemia-reperfusion." (PMID 34526897, 2021). "NLRP3 inflammasome has been demonstrated to be associated with neuroinflammation and cerebral ischemia, and plays an important role in cerebral ischemia and peaks 24 h after MCAO." (PMID 32153398, 2020). "In cerebral ischemia, the importance of NLRP3 inflammasome activation as a pathogenic mediator has been suggested." (PMID 33202644, 2020). "The pathogenic role of LPA1 in cerebral ischemia was associated with NLRP3 inflammasome activation, including NLRP3 upregulation, ASC speck formation, caspase-1 activation, and IL-1β maturation in a post-ischemic brain." (PMID 33202644, 2020). "NLRP3+ cell counts showed that cerebral ischemia caused the activation of the NLRP3 inflammasome in the penumbra of the ischemic cortex." (PMID 31920554, 2019). "The mechanism may be downregulation of NFΚB/NLRP3/Caspase-1/GSDMD pathway protein expression and regulation of NLRP3 inflammasome-mediated pyroptosis associated with cerebral ischemia-reperfusion." (PMID 39199474, 2024). "Additionally, HIF‐1α signalling has been implicated in NLRP3 inflammasome activation, with its inhibition shown to mitigate macrophage NLRP3 inflammasome activation in cerebral ischemia‐reperfusion models, suggesting a broader role in inflammatory pathologies." (PMID 39623879, 2024). "Recent studies demonstrated that NLRP3 inflammasome deficiency reduces cerebral ischemia-reperfusion injury by inhibiting ferroptosis, which may be achieved through the mechanism of the Keap1-Nrf2 pathway." (PMID 36818726, 2022). "When TXNIP and NLRP3 are decreased, tissue damage associated with cerebral ischemia is reduced." (PMID 33567593, 2021). "Importantly, all these signals are activated after brain ischemia, which likely underlies activation of NLRP3 inflammasome in the brain after CA/CPR, as observed here." (PMID 32867797, 2020). "Thus, the present study aimed to investigate whether LCN2 is involved in astrocyte pyroptosis and whether it is associated with NLRP3 inflammasome activation post-cerebral ischemia/reperfusion injury." (PMID 37353794, 2023). "Finally, ISO pretreatment inhibited NLRP3 inflammasome activation in the retina after cerebral ischemia which may underlie its protective effects." (PMID 34305534, 2021). "Importantly, the pathogenic role of LPA1 signaling in cerebral ischemia could be closely associated with NLRP3 inflammasome activation (the current study)." (PMID 33202644, 2020). "In addition, the NLRP3 inflammasome is associated with HMGB1 activation during cerebral ischemia." (PMID 33384585, 2020). "This study confirmed that quercetin can directly bind to the NLRP3 protein and alleviate cerebral ischemia-induced inflammatory injury by inhibiting the activation of the NLRP3/Caspase-1/GSDMD pyroptosis axis and the release of downstream inflammatory factors." (PMID 41892344, 2026). "In the pathological cascade of cerebral ischemia, the pyroptosis axis mediated by the NLRP3 inflammasome in activated microglia is a core link driving neuroinflammation and secondary brain injury." (PMID 41892344, 2026).
Cerebral ischemia (continued). "Emerging evidence suggests that FOXP1 suppresses NLRP3 inflammasome activation, mitigating brain ischemia–reperfusion injury." (PMID 41596522, 2026). "It was reported that Epimedium aqueous extract, which contains Icariin as a major active constituent, ameliorates cerebral ischemia/reperfusion injury through inhibiting ROS/NLRP3-mediated pyroptosis." (PMID 41322003, 2025). "Several recent studies have revealed that NLRP3 inflammasome-mediated pyroptosis is observed in the cerebral ischemia–reperfusion model and in ionizing radiation-induced lung injury." (PMID 40936902, 2025). "In line with our results, earlier research has shown that blocking NLRP3 inflammasome-driven pyroptosis can significantly reduce brain ischemia-reperfusion injury." (PMID 40606597, 2025). "Recent research has discovered that the active ingredients in some traditional Chinese medicine extracts can protect against brain ischemia-reperfusion injury by preventing NLRP3 inflammasome-driven pyroptosis." (PMID 40606597, 2025). "This suggests that resveratrol has a protective effect on cerebral ischemia-reperfusion injury by inhibiting the activation of NLRP3 inflammasome by inhibiting Sirt1-dependent autophagy activity." (PMID 38601463, 2024). "Murine models of myocardium infarction and cerebral ischemia are frequently used to study the activation of NLRP3 inflammasome related to ischemic insults." (PMID 38909168, 2024). "Overall, these results underscore the neuroprotective role of astrocyte-derived exosomes delivering miR-378a-5p, which alleviates OGD-induced neuronal injury and pyroptosis by suppressing the NLRP3 signaling pathway and ameliorating cerebral ischemia." (PMID 39176087, 2024). "The aberrant expression and function of NLRP3 inflammasome-mediated inflammation in cerebral ischemia have garnered considerable attention as a recent research focus." (PMID 38601463, 2024). "Studies have shown that autophagy has a pivotal role in maintaining neuronal hemostasis and inhibits NLRP3 inflammasome-mediated inflammation following cerebral ischemia." (PMID 37848698, 2024). "Emerging evidence strongly implicates the NLRP3 inflammasome as a potential therapeutic target, playing a key role in cerebral ischemia and reperfusion injury." (PMID 38601463, 2024). "The aim of reviewing natural compounds is to identify potential lead compounds capable of inhibiting the NLRP3 inflammasome in cerebral ischemia." (PMID 38601463, 2024). "In acute cerebral ischemia, autophagy negatively regulates the inflammatory response by acting a role in the inhibition of NLRP3-mediacted neuroinflammation." (PMID 38745316, 2024). "Despite upregulation, the knockdown of miR-423-5p in rats improved brain water content and nerve damage in cerebral ischemia and inhibited NLRP3 inflammasome activation." (PMID 38421496, 2024). "Accordingly, this review provides a comprehensive summary of the signaling pathways, pathological mechanisms, and intricate interactions involving NLRP3 inflammasomes in cerebral ischemia-reperfusion injury." (PMID 38601463, 2024). "In line with our results, recent studies described the beneficial activity of a modified citrus pectin in the inhibition of the NLRP3 inflammasome and NF-kB pathway activation in microglia during cerebral ischemia." (PMID 38391968, 2024). "In vitro and in vivo models of cerebral ischemia, in addition to mTOR and NLRP3 inflammasome, PRNP, sphingosine kinase 1 (SphK1), DJ-1 and other signals participate in the regulation of neuroinflammation through autophagy as well." (PMID 37548945, 2024). "This review provides a summary of the neuroinflammatory mechanism mediated by the NLRP3 inflammasome in the context of cerebral ischemia-reperfusion injury." (PMID 38601463, 2024). "During cerebral ischemia–reperfusion injury, argon application alleviates neuroinflammation via suppressing M1 microglial polarization and NF-κB/NLRP3 inflammasome signaling." (PMID 38745316, 2024).
Cerebral ischemia (continued). "The NF-κB/NLRP3/Caspase-1/GSDMD pathway is involved in cerebral ischemia-reperfusion injury, and its related molecules have become experimental targets for alleviating cerebral ischemia-reperfusion injury." (PMID 39199474, 2024). "Currently, there is growing interest in exploring natural plant products for the treatment of NLRP3 inflammasome-mediated neuroinflammation in cerebral ischemia/reperfusion injury." (PMID 38601463, 2024). "Similar results were discussed in models of cerebral ischemia where inhibition of NLRP3 inflammasome decreased neuronal death, M1 microglial polarization, and increased blood-brain barrier integrity." (PMID 38909168, 2024). "Conversely, the downregulation of miRNA-20b reduced IL-1β and IL-18 levels, ATP, and ROS by repressing the NLRP3 pathway in cerebral ischemia." (PMID 38421496, 2024). "When NLRP3 activation was inhibited, astrocyte pyroptosis was suppressed, suggesting that NLRP3 initiation is essential in astrocyte pyroptosis following cerebral ischemia/reperfusion injury." (PMID 37353794, 2023). "In summary, our results revealed that cerebral ischemia induced the upregulation of ROS and NLRP3, Caspase-1, and IL-1β expression, whereas HS reduced the levels of all these factors." (PMID 37371417, 2023). "A recent study in cerebral ischemia/reperfusion injury suggested that inhibition of TXNIP/NLRP3 promoted the transition of microglia from M1 to M2 phenotype." (PMID 36875102, 2023). "ROS is considered a signal molecule to activate NLRP3; thus, the ROS/NLRP3/pyroptosis axis plays a vital role in the pathogenesis of cerebral ischemia/reperfusion injury (CIRI)." (PMID 37237865, 2023). "Umbelliferone protected against cerebral ischemia reperfusion-induced injury by inhibiting thioredoxin-interactive protein and NLRP3 inflammasome activation and upregulating PPAR-γ activity." (PMID 37111279, 2023). "For instance, estrogen inhibits global cerebral-ischemia-induced NLRP3 inflammasome activation and proinflammatory cytokine expression in glia." (PMID 36899944, 2023). "Through the inhibition of the TLR4/NF-κB signaling pathway, meisoindigo effectively reduced cerebral ischemia injury by preventing NLRP3 inflammasome activation and the polarization of microglia M1." (PMID 38273974, 2023). "LRP1 activation has been shown to attenuate oxidative stress, neuroinflammation and apoptosis and can improve short- and long-term neurological deficits and positively influence mortality after cerebral ischemia by inhibiting the TXNIP/NLRP3 signaling pathway." (PMID 38067191, 2023). "Considered together, these results suggest that HS can downregulate the production of ROS and the expression of NLRP3, Caspase-1, and IL-1βin the peri-infarction cortex after cerebral ischemia." (PMID 37371417, 2023). "LCN2/24p3R mediates astrocyte pyroptosis via NLRP3 inflammasome activation following cerebral ischemia/reperfusion injury." (PMID 37353794, 2023). "Taken together, these findings suggested that LCN2/24p3R mediates pyroptosis in astrocytes via the NLRP3 inflammasome after cerebral ischemia/reperfusion injury." (PMID 37353794, 2023). "A previous study reported that PNS downregulated expression of NLRP3 inflammasome pathway-related proteins in cerebral ischemia/reperfusion." (PMID 37158944, 2023). "Nervous system deterioration after cerebral ischemia can be prevented by inhibiting the expression of NLRP3." (PMID 37373274, 2023). "Both NLRP3 and NLRP3-dependent genes of the inflammasome are significantly elevated during the first phase of cerebral ischemia, intensifying cerebral ischemic injuries." (PMID 37915409, 2023). "ROS, NLRP3, Caspase-1, and IL-1β expression increased after cerebral ischemia, and this was reversed by HS treatment." (PMID 37371417, 2023).
Cerebral ischemia (continued). "Both NLRP2 and NLRP3 have been shown to participate in the proinflammatory events related to experimentally induced cerebral ischemia after cerebral ischemia-reperfusion injury and acrolein-induced astrocytic inflammation in brain affected by ischemic stroke." (PMID 35783102, 2022). "Meanwhile, NLRP3 knockdown in vivo significantly inhibited microglia/macrophage pyroptosis and ameliorated cerebral ischemia injury." (PMID 36035210, 2022). "FK866 inhibited Drp1-mediated activation of NLRP3 and pyroptosis and protected against cerebral ischemia-reperfusion injury." (PMID 36467606, 2022). "An earlier study showed that D-carvone suppresses the NLRP3 inflammasome-induced inflammation in cerebral ischemia/reperfusion." (PMID 36294936, 2022). "D-Carvone exhibited neuroprotective actions via constraining the cerebral ischemia/reperfusion-induced inflammatory response via deterring the TLR4/NLRP3 signaling pathway." (PMID 36294936, 2022). "After cerebral ischemia, the changes in the intracellular microenvironment trigger the NLRP3 inflammasome (NLRP3/ASC/CASPASE-1) activation, which leads to the secretion of IL-1β and IL-18 and finally mediated cell death." (PMID 36091745, 2022). "NLRP3 inflammasome knockout not only is beneficial for cerebral ischemia–reperfusion injury but also reduces the severity of poststroke lung injury by reducing brain damage." (PMID 35432726, 2022). "(ii) Which role do NLRC4 and AIM2 play upon functional inhibition of microglial NLRP3 after cerebral ischemia?" (PMID 34628598, 2022). "A recent study describes a novel mechanism by which D-carvone protects against cerebral ischemia/reperfusion-induced inflammatory response by suppressing the TLR4/NLRP3 cascade." (PMID 35625467, 2022). "Another hormone, adiponectin, regulated cerebral ischemia-reperfusion by blocking the NLRP3 inflammasome through regulating AMPK and GSK-3β phosphorylation and Nrf2 translocation." (PMID 35418995, 2022). "In cerebral ischemia–reperfusion (I/R) injury, NLRP3 inflammasomes were accumulated in neurons and induced immune cell infiltration to destroy the integrity of the blood–brain barrier." (PMID 36278219, 2022). "In this study, we explored the effects of NBP on the microglial NLRP3 inflammasome after cerebral ischemia in transient middle cerebral artery occlusion (tMCAO) mice." (PMID 36013423, 2022). "First, our findings demonstrated that NLRP3 knockout had a protective effect against cerebral ischemia–reperfusion injury after MCAO." (PMID 35432726, 2022). "Our previous study found that acacetin inhibited the Nod-like receptor pyrin domain containing 3 (NLRP3) signaling pathway after cerebral ischemia–reperfusion injury." (PMID 36382256, 2022). "RvD1 ameliorated neuronal death, decreased IL1β, TNFα, malondialdehyde, MDA, and NLRP3 protein in rats with cerebral ischemia/reperfusion injury." (PMID 36670960, 2022). "Other scholars have demonstrated that CHR curbs the activation of NLRP3 inflammasome and guards against brain tissue injury during cerebral ischemia/reperfusion." (PMID 35599576, 2022). "Inhibition of NLRP3 activation can reduce neuronal injury and exert a neuroprotective effect after CIRI, while ERS and autophagy promote the death of neurons after cerebral ischemia through the NLRP3 inflammasome." (PMID 35602556, 2022). "Bruton’s tyrosine kinase (BTK) is a class of tyrosine kinases involved in the activation of the NLRP3 inflammatory complex in brain ischemia and reperfusion, resulting in the expression of mature caspase-1, as well as increased levels of IL-1." (PMID 36552584, 2022). "In a cerebral ischemia model, the researchers observed the downregulation of MicroRNA-139-5p (miR-139-5p) and the pyroptosis induced by the activation of NLRP3." (PMID 36552584, 2022). "A previous study suggested that phthalide derivative CD21 alleviated the overactivation of astrocytes by inactivation of NF-κB signaling pathway and NLRP3 inflammasome after cerebral ischemia." (PMID 34362408, 2021).
Cerebral ischemia (continued). "Studies have shown that Nrf2 can inhibit the formation of NLRP3 inflammasomes through thioredoxin-1 (Trx1)/thioredoxin interacting protein (TXNIP) during cerebral ischemia-reperfusion injury, thereby playing a protective role in the brain." (PMID 34526897, 2021). "NLRP3 inflammasome is widely observed in cerebral ischemia tissues and reported to play a significant role in CNS injury in ischemic diseases." (PMID 34852714, 2021). "Kv1.3 channel blocker, PAP-1, reduces cerebral ischemia-reperfusion injury by remodeling the M1/M2 phenotype and inhibiting the activation of microglia NLRP3 inflammasome." (PMID 35008558, 2021). "In this manuscript, we summarize the existing evidence regarding the composition and activation of the NLRP3 inflammasome, the molecules involved in inflammatory pathways, and corresponding drugs or molecules that exert effects after cerebral ischemia." (PMID 34059091, 2021). "Studies have suggested that intermittent fasting, intravenous immunoglobulin, minocycline, emodin, tyrosine kinase can all inhibit the activation of NLRP3 inflammasome in cerebral ischemia-reperfusion." (PMID 34526897, 2021). "Salvianolic acids alleviate cerebral ischemia/reperfusion injury by inhibiting NLRP3 inflammasomes in microglia." (PMID 34356130, 2021). "NLRP3 knockdown after cerebral ischemia can significantly reduce cerebral infarction and damage to the blood-cerebrospinal fluid barrier and improve the brain damage to mice after cerebral ischemia." (PMID 34227902, 2021). "Although the mechanism is not clear, l-homocarnosine reduces the inflammatory response in cerebral ischemia-reperfusion injury by reducing the expression of NLRP3." (PMID 35008558, 2021). "This study suggests that Nrf2 inhibits NLRP3 inflammasome activation during cerebral ischemia/reperfusion injury by regulating the Trx1/TXNIP complex." (PMID 34526897, 2021). "It was found that SIRT1 inhibited the activation of NLRP3 and the secretion of IL-1β in cerebral ischemia." (PMID 34039367, 2021). "In cerebral ischemia, NLRP3 inflammasome activation evoked the cleavage of caspase-1, thereby cleaving GSDMD, pro-IL-1β, and pro-IL-18 to GSDMD-N, mature IL-1β, and IL-18, respectively." (PMID 34630845, 2021). "For cerebral ischemia-reperfusion therapy targeting NLRP3, its small molecule inhibitor, MCC950, has been proposed." (PMID 35008558, 2021). "Cerebral ischemia induces activation of the inflammasome and is characterized by an increase in NLRP3 and TXNIP." (PMID 33567593, 2021). "Following cerebral ischemia, treatment with different compounds, such as melatonin, methylene blue, and rapamycin, promotes the inhibition of ROS generation and NLRP3 inflammasome activation by enhancing the mitophagy process." (PMID 33572080, 2021). "BTK is a tyrosine kinase that participates in the activation of the NLRP3 inflammasome, which in turn leads to the activation of caspase-1 and the production of mature IL-1β in the process of cerebral ischemia." (PMID 35008558, 2021). "The NLRP3 inflammasome is first activated in microglia shortly after brain ischemia-reperfusion injury, and then expressed primarily in neurons and in microvascular endothelial cells but mainly in neurons." (PMID 35008558, 2021). "Ito and colleagues showed that ibrutinib, a potent BTK inhibitor, inhibits NLRP3 inflammasome signaling in a focal brain ischemia-reperfusion model." (PMID 35008558, 2021). "While an axis miR-497/TXNIP has been described in diabetic nephropathy, other studies report the role of different miRNAs, including miR-17 in the TXNIP/NLRP3 signaling pathway in inflammation-induced kidney injury or brain ischemia." (PMID 33567593, 2021). "In the present study, we assessed the potential roles of QNDP on NLRP3 inflammasome in cerebral ischemia." (PMID 32153398, 2020). "In middle cerebral artery occlusion (MCAO) rat model, Arctigenin showed neuroprotective effects against cerebral ischemia via SIRT1-dependent inhibition of NLRP3 inflammasome." (PMID 33574759, 2020).